MIR1193 (microRNA 1193)
Synonyms: hsa-mir-1193
Gene: MicroRNA gene on chromosome 14 (101,030,052 to 101,030,129, forward strand). Ensembl gene ENSG00000221036.
Homologues: Orthologues: chimpanzee MIR1193 (100% identical).